IL1B (interleukin 1 beta)
Diseases named in the same sentence as IL1B in open-access papers (continued):
Sharing a sentence is not in itself a finding about the gene and the disease.
tumor (continued). "β2AR signaling can also polarize macrophages from M1 to M2 type, thereby enhancing anti-inflammatory cytokines like IL-10, IL-4 & IL-13, and decreasing pro-inflammatory cytokines like INFγ, TNFα, IL1β, CCL2, CCL3 and CCL4 to cause tumor progression." (PMID 37006295, 2023). "When tumor cells undergo pyroptosis, it is often attended by the release of the inflammatory cytokines IL-1β and IL-18, which possess pro-tumor and tumor-suppressive effects." (PMID 37705746, 2023). "As chronic inflammation plays a decisive role in cancer development, NLRP3, IL-18, and IL-1β have been the focus of tumor researchers for over a decade." (PMID 36766797, 2023). "When co-cultured with BC cells, CAAs increased the secretion of IL-1β, which is an important factor and driver of tumor malignance." (PMID 36765683, 2023). "Among genes thought to be related to the M1-macrophage phenotype, expression of the IL-8 gene increased with tumor progression together with that of the IL-1β gene." (PMID 37441079, 2023). "IL-1β and IL-6 are cellular inflammatory components, and these factors modify the perivascular endothelial cell surroundings and promote tumor development." (PMID 36976205, 2023). "In this study, a significant reduction in NLRP3, ASC, IL-1β, and IL-18 expression was shown in the tumor’s samples from BAY-117082-treated mice compared to the OSCC group." (PMID 37345134, 2023). "IL-1β expression at the transcript level and protein secretion increased in NFs upon co-culture with patient-derived 3D tumor spheroids." (PMID 37460545, 2023). "Expression of the IL-1β gene in myeloid cells was thus found to be increased in tumor tissue relative to normal lung tissue and to increase with disease progression." (PMID 37441079, 2023). "The stabilization of target genes responsible for encoding glycolytic enzymes and the pro-inflammatory cytokine IL-1β, which can impede tumor cell growth, enhance tumor survival, and intensify inflammation, is facilitated by this process." (PMID 37808079, 2023). "Previous reports have shown that IL-1β is produced by tumor cells and contributes to the immunosuppressive microenvironment in PDAC." (PMID 35737090, 2023). "P2X7R blockade likely hinders NLRP3 inflammasome-controlled release of tumour-promoting mediators such as IL-1β." (PMID 37225786, 2023). "It is worth noting that in OS, IL-1β is responsible for the increased expression of programmed cell death ligand 1 (PD-L1), which is associated with cancer cell evasion, highlighting the role of IL-1β in tumor relapse." (PMID 37760046, 2023). "Furthermore, to better understand the association between antidepressant effects on tumor pathology and immune system activity, the T-cell proliferative response to concanavalin A (Con A), and the production of anti- and pro-tumoral cytokines: IL-1β, IL-10, and IFN-γ were also studied." (PMID 37409130, 2023). "Secreted form of IL-1β can diffuse into the tumor microenvironment and has been discussed to potentiate molecules from malignant stroma cells that promote invasiveness and metastasis." (PMID 38187473, 2023). "A global proteome analysis and bioinformatic approach revealed the regulation of proteins involved in the formation of metastases, tumor cell invasion, and apoptosis, like keratin 81, CrkII, IL-1β, and cathepsin B." (PMID 38248645, 2023). "We also verified in our clinical specimens that the levels of IL-1β in PAs were highly correlated with tumor bone invasion and PKCθ levels." (PMID 36900414, 2023). "Emerging evidence suggests that IL-1β promotes tumor progression via various mechanism that stimulates tumor angiogenesis and recruitment of myeloid cells." (PMID 37932814, 2023). "Red blood cells and hemoglobin can directly generate active IL-1β, which is required for angiogenesis and the invasiveness of various tumor cells in vivo by activating NF-κB to generate pro-IL-1β." (PMID 37894821, 2023).
tumor (continued). "IL1β also plays an important role in tumor cell migration and the establishment of metastatic deposits." (PMID 37065483, 2023). "Vγ6+ cells express constitutively high levels of PD-1, whereas Vγ4+ cells upregulate TIM-3 in response to tumor-derived IL-1β and IL-23." (PMID 36480166, 2023). "Accordingly, TGF-β1, IL-10 and CCL2 protein levels were significantly increased, and TNFα, IL-6, IL-1β and IL-12p40 protein levels were significantly decreased in tumor tissues in mice with MO-Mettl3 macrophages compared with mice with MO–nc macrophages." (PMID 37402945, 2023). "Tumor spheroids treated with conditioned media from CAFs pre-treated with IL-1β grew larger than those treated with conditioned media from untreated CAFs." (PMID 37460545, 2023). "This induces tumor cells to increase the secretion of chemotherapy resistance inducer IL-1β, thus promoting the development of tumor chemotherapy resistance." (PMID 37165428, 2023). "AIM2-/- and caspase 1-/- BMDM, treated with LPS and either dsDNA or tumor CM, similarly produced significantly less IL-1β compared to WT BMDM." (PMID 37449203, 2023). "IL-1β plays a key role in promoting the different stages of bone metastasis in BC by affecting primary tumor growth and angiogenesis, promoting tumor cell movement into the circulating blood, and promoting tumor cell colonization in the bone microenvironment." (PMID 36765683, 2023). "Functionally, M1 (F4/80+CD11b+CD86+) can kill tumor cells by expressing inducible nitric oxide synthase (iNOS), reactive oxygen species (ROS), and cytokines such as IL-1β, tumor necrosis factor-alpha (TNF-α), IL-12 and IFN-γ." (PMID 37415162, 2023). "We found that the proportion of CD8+ T cells expressing proinflammatory/pro‐tumour cytokines/molecules was higher than that of other immune cells, especially Ltb, Pdcd1, Cxcr6 and Il1b." (PMID 37997519, 2023). "In support of this, SIK1 and SIK3 were shown to control IL-6 production in tumor cells and IL-6 and IL-1β production in Raw264.7 macrophages." (PMID 37140993, 2023). "There is a marked reduction (p < 0.001) in the expression of IL-1α and IL-1β in the tumor tissues of Anakinra treated mice compared to all of the other groups." (PMID 38152619, 2023). "Mechanistically, tumor-infiltrating IL-1β activated IL-17A+ γδ T cells, enhancing the priming and recruitment of IFN-γ-producing CD8+ T cells that exert antitumor effects." (PMID 37631976, 2023). "To further investigate the mechanisms underlying IL‐1β‐mediated immunosuppression, we focused on how IL‐1β reshaped the gene expression profile of tumor cells." (PMID 37009412, 2023). "During incipient neoplasia, dermal fibroblasts can be educated and transformed into CAFs by IL-1β-triggered NF-κB activation." (PMID 36418470, 2023). "In contrast, the overexpression of IL‐1β substantially exacerbated tumor growth in vivo, suggesting that the regulation of tumor growth by IL‐1β is related to the tumor microenvironment." (PMID 37092583, 2023). "Here, we report that IL‐1β is one of the most abundant cytokines secreted by THP1‐derived Mφ (THP1 Mφ) following direct co‐culturing with tumor cell lines and functions as a critical PD‐L1‐inducer in tumor cells to blunt the cytotoxicity of T cells." (PMID 37009412, 2023). "Although mounting studies confirmed the role of IL-1β in promoting tumor progression, the opposite function of IL-1β has also been proposed." (PMID 36823153, 2023). "In tumor tissue with the presence of red blood cells, levels of IL-6, IL-12, IL-1β, and TNF-α are increased." (PMID 37894821, 2023). "IL‐1β, in turn, drove an immune inhibitory phenotype on tumor cells, especially on the increase in PD‐L1, by activating the NF‐κB signaling pathway." (PMID 37009412, 2023). "The attenuated hematopoietic cell-derived IL-1β and IL-18 at the tumor site of Nlrp3−/− mice are found to be the key for inflammation and tumorigenesis." (PMID 36932407, 2023).
tumor (continued). "Profiling of immune-related proteins with NanoString GeoMx indicated that anti–IL-1β–treated tumors had increased levels of granzyme B, a serine protease important for immune cell–mediated cytotoxicity of tumor cells." (PMID 37966120, 2023). "TNF-α and IL1-β are pro-inflammatory cytokines that increase macrophages’ cytotoxicity against tumor cells." (PMID 36903405, 2023). "Taken together, these results demonstrate that IL‐1β is secreted by Mφ and is pivotal in regulating PD‐L1 expression by tumor cells in the TME." (PMID 37009412, 2023). "IL-1β and coculture of tumor cells with macrophages enhances the proliferation of tumor cells which is AIM2 and caspase 1/11 dependent (Gigure 6)." (PMID 37449203, 2023). "The IL-1β is able to stimulate the secretion of IL-6 by fibroblasts, which in turn promotes tumor angiogenesis, metastasis, and invasion through EMT, demonstrating a direct correlation with the neovascularization process." (PMID 37445908, 2023). "Immature myeloid cells become immunosuppressive MDSC under the combined influence of tumor-derived IL-1β, IL-6, and S100A8-9, as well as IFN-β, IL-4, IL-13, and IL-10 released by activated T cells." (PMID 37415162, 2023). "Next, we performed coculture experiments with PDGFB-driven primary tumor cells (GSCs) and BMDMs and measured both intracellular (pro–IL-1β) and secreted IL-1β." (PMID 37733448, 2023). "M1 macrophages produce various pro-inflammatory cytokines, such as tumor necrosis factor-alpha (TNF-α), interleukin-1 beta (IL-1β), and interleukin-6 (IL-6), which have been shown to inhibit tumor growth." (PMID 37999824, 2023). "Pro-inflammatory cytokines and chemokines, such as IL-6, IL-8, IL-1β, and TNF-α, can activate stromal cells, including CAFs and tumor-associated macrophages (TAMs)." (PMID 37760801, 2023). "For DCs and macrophages, secretion of IL-1β and IL-18 is accompanied by antigen presentation or T cell recruitment, while inflammasome activation in tumor cells is accompanied by immunosuppressive signals such as PD-1/PD-L1." (PMID 36932407, 2023). "IL-1β enhances tumor cell proliferation, migration and invasion while coculture of tumor cells with macrophages enhances the proliferation of tumor cells, which is AIM2 and caspase 1/11 dependent." (PMID 37449203, 2023). "Suppression of IL-1β expression decrease tumor growth and inhibit perfusion of tumor cells from the primary location into circulation." (PMID 37700002, 2023). "MMPs have the ability to degrade extracellular matrix (ECM) proteins; remodel the tumor stroma; and promote the activation of cytokine production, such as that of IL-1β." (PMID 37542283, 2023). "Genetic loss or locally antagonizing IL-1β/IL-1R1 leads to reduced MDM infiltration, diminished tumor growth, and reduced exhausted CD8+ T cells and thereby extends the survival of tumor-bearing mice." (PMID 37733448, 2023). "IL1β is an IL predominant in chronic inflammation and it promotes tumour initiation and progression." (PMID 36900301, 2023). "For example, some studies have shown that blocking IL-1β or IL-18 can inhibit tumor growth or metastasis, while others have proven that inhibiting NLRP3 inflammasome can enhance tumor growth or metastasis." (PMID 37715239, 2023). "Inhibiting the expression of IL-1β has been shown to reduce tumor growth and prevent the shedding of tumor cells from the primary site into circulation." (PMID 37304133, 2023). "For example, TAMs secrete interleukin 1β (IL-1β) in response to the acidic conditions, which then intensely promote angiogenesis, tumor cell migration, tumor cell proliferation, and metastasis." (PMID 38067178, 2023). "Within the lung microenvironment, γδ T cells are activated to produce IL-17A by tumor-derived or microbiota-induced IL-1β and IL-23, two cytokines with well-established influence on IL-17A–producing γδ T cells." (PMID 36480166, 2023).
tumor (continued). "Prior to conducting the assay, we identified a subset panel of factors known to mediate the induction of apoptosis in tumor cells: IL-27, IL-1b, IL-2, CXCL10, IL-12p70, G-CSF, IFN-g, TNF-a, IFN-a, CCL2, IL-9, TNF-b, TRAIL, IL-18, IL-21, TSLP." (PMID 37468934, 2023). "Zheng and colleague found that the integration of CY-09 to the classic gemcitabine treatment dampens tumor resistance by blocking IL-1β/EMT/Wnt/β-catenin signaling pathway in BC." (PMID 37891577, 2023). "Collectively, our study highlights the importance of IL1R1 and IL-1β signaling in the fibroblast compartment, especially in regard to driving immunosuppression and tumor growth." (PMID 37460545, 2023). "In metastatic breast cancer, the NLRP3 inflammasome inhibition delays tumor growth by reducing IL-1β in metastatic breast cancer." (PMID 37705746, 2023). "To further confirm the involvement of IL-1β in the impaired STC in the tumor-bearing mice, we performed the same strong before weak STC paradigm in mice receiving IL-1β neutralization antibody." (PMID 37400621, 2023). "The secretion of pro-inflammatory factors such as TNF-α, IL-1β and IL-6 regulated the tumour microenvironment and exerted anti-tumour effects." (PMID 37386139, 2023). "Anti‐IL‐1β antibody exerts a tumor‐inhibitory impact and displays a synergistic effect with ADT and ICB on advanced PCa." (PMID 37092583, 2023). "Supporting our findings, other studies showed an inverse correlation between the expression of ER-α and tumor secretion of the NLRP3 product IL-1β in BC tumor tissues." (PMID 36902278, 2023). "First, we do not have any in vivo evidence of a direct relation between pathogenic PD-L1 expression induced by IL-1β and IFN-γ and actual tumor development." (PMID 37441079, 2023). "To further test this, we sought to identify the host cells that respond to KRASMUT tumor cells with NF-κB activation, since the transcription factor controls IL-1β transcription and is central to innate immune responses." (PMID 36980752, 2023). "F4/80 + macrophages with increased M1 marker CD86, activation marker iba-1 expression, and pro-inflammatory cytokine IL-1β production were detected in tumor tissue." (PMID 38001420, 2023). "As a consequence, IL-1β is secreted in the tumor environment, which in turn enhances the proliferation of metastatic cells." (PMID 37749707, 2023). "IL-1β is another cytokine overexpressed in lung tumors and is involved in tumor development and metastasis by inducing growth factors, such as vascular endothelial growth factor, prostaglandin E2 (PGE2), and transforming growth factor β." (PMID 37373987, 2023). "In a study investigating in vitro cytokine production, tumour-infiltrating lymphocytes produced a higher amount of IL1β and IL6 compared to peripheral blood leukocytes in OSCC patients." (PMID 36900301, 2023). "By influencing the behavior of these cells, IL-1β helps to shape the overall immune response to the tumor, making it an important player in the complex interplay between the immune system and cancer." (PMID 37077909, 2023). "Activated NLRC4 inflammasomes from tumor-infiltrating myeloid cells produce IL-1β, which promotes vascular endothelial growth factor A (Vegfa) expression in adipocytes facilitating angiogenesis, a key step in metastasis." (PMID 36932407, 2023). "We anticipate that the roles of TNFα and IL-1β in cisplatin-induced tumour vascular damage will be further investigated in the future." (PMID 37056922, 2023). "Both tumor and stromal cells can release IL-1β, generating an immunosuppressive TME enriched in TAMs, myeloid-derived suppressor cells (MDSCs), and Treg cells." (PMID 37190141, 2023).
tumor (continued). "Innate immune cells, such as M1 macrophages, tumor associated granulocytes, and classical monocytes, are known to exert anti-tumor effects with increased proinflammatory cytokines, including IL-1β, IL-6, and TNF-α, and reactive oxygen species." (PMID 38125025, 2023). "The results showed that IL‐1β blockade significantly decreased the expression of PD‐L1 in tumor tissues, and the frequency of Mφ was much less in anti‐IL‐1β antibody‐treated tumor tissues, compared to non‐treatment." (PMID 37009412, 2023). "TAMs and MDSCs were enhanced in the immunosuppressive environment induced by IL‐1β, which promotes tumor growth." (PMID 37752941, 2023). "We also evaluated variation in the levels of inflammatory factors such as amylase (AMY), TNF-α, and IL-1β in the blood of tumor-bearing mice after different treatments." (PMID 37649601, 2023). "IL-1β is involved in inflammation and tumor growth by stimulating angiogenesis in the cancerous cells." (PMID 37188770, 2023). "Tumor-associated macrophages with protumor and inflammatory characteristics (VEGFhigh/CXCL8+/IL1β+) are found in solid ovarian tumors." (PMID 37765018, 2023). "Several inflammatory factors related to tumours, including interleukins (IL-6, IL-10, IL-17, IL-1β), TGF-β, IFN-γ, TNF-α, VEGF, and MMPs, are also the cancer-associated genes." (PMID 37742025, 2023). "Proinflammatory M1‐like markers, such as CD80, TNFα, CXCL10, tend to be associated with an antitumor immune response, while macrophages expressing other proinflammatory cytokines (IL‐1β, IL‐6) can mediate tumor cell migration and cancer progression." (PMID 38037545, 2023). "IL-1β secreted by TAMs and neutrophils was found to promote cancer cell proliferation and recruit myeloid-derived suppressor cells (MDSCs) supporting tumour growth." (PMID 37370746, 2023). "For example, NLRP3 inflammasomes in DCs are activated allowing for IL-1β secretion when ATP from dying tumor cells acts on P2 purinergic receptors (P2X7) purinergic receptors from DCs." (PMID 36932407, 2023). "BMDM cocultured with tumor cells induced both IL-1β expression and secretion; however, this effect was only observed using PDGFB mGBM tumors, but not Nf1-silenced mGBM cells." (PMID 37733448, 2023). "The in vivo administration of the anti‐IL‐1β antibody enhanced the therapeutic efficacy of anti‐PD‐1 in tumor cell‐derived xenograft models." (PMID 37009412, 2023). "Taken together, we elucidate that tumor cell‐derived lactate enhances IL‐1β transcription and secretion by Mφ." (PMID 37009412, 2023). "Since IL-8 is deleted in mice, IL-1β mRNA level was analysed in tumour-bearing mice treated with Doc by RT‒qPCR." (PMID 37550397, 2023). "M1-macrophages exert anti-tumor effects by promoting increased expression and release of cytokines such as IL-1β, TNF-α, IL-6, and IL-12 and elevating the helper T cell 1 (Th1)-mediated immune response." (PMID 37588995, 2023). "IL-1α and IL-1β immune-reactivities are predominant in the cytoplasm of the macrophages, lymphocytes, and tumor cells." (PMID 38152619, 2023). "As IL-18 has recently attracted attention in tumor biology, and the implication of IL-1β was extensively discussed elsewhere, the rest of this review will focus on the role of IL-18 in cancer progression." (PMID 37298187, 2023). "NLRP3 expression and IL-1β secretion of BC tumors promote myeloid-derived suppressor cell (MDSCs) and tumor-associated macrophage (TAM) infiltration to the tumor microenvironment and facilitate an inflammatory microenvironment for cancer progression." (PMID 36902278, 2023). "As expected, tumor growth was sloped down following anti‐IL‐1β antibodies treatment, similar to the administration with anti‐PD‐1 antibodies." (PMID 37009412, 2023). "Blocking IL-1β signaling using neutralization antibody restored the STC in the tumor-bearing mice, demonstrating the critical role of IL-1β in hippocampus cognitive dysfunction." (PMID 37400621, 2023).